REN (renin)
Diseases named in the same sentence as REN in open-access papers (continued):
Sharing a sentence is not in itself a finding about the gene and the disease.
Hypertension (continued). "It has been demonstrated that 2K1C hypertension is mainly initiated by the activation of the renin-angiotensin system rather than by impairment of renal function." (PMID 24502628, 2014). "For that reason, we treated our patient’s hypertension with a combination of calcium channel blocker (amlodipine) and α-blocker (prazosin), which allowed us to sample renin and aldosterone without interference." (PMID 25177679, 2014). "In vitamin D receptor knock-out mice renin expression is highly increased leading to hypertension and LV hypertrophy and in mice active vitamin D analogue treatment suppresses renin expression, independent of PTH." (PMID 24661355, 2014). "Unlike db RAS mice, db UNX mice did not develop significant hypertension, and plasma renin content was lower than that observed in db RAS or db sham." (PMID 24708836, 2014). "The level of renin and angiotensin in an injured artery model is not as high as the level in long-term hypertension, which has sustained high levels of Ang II." (PMID 24987435, 2014). "In contrast, HD-OVE mice developed profound hypertension from 16–20 weeks of age (>180 mmHg) that dramatically exceeded that of non-diabetic renin-expressing mice." (PMID 25514595, 2014). "Therefore, the renin-angiotensin system inhibitors, including ACE inhibitors and AT-1R blockers (ARB), are used widely for the treatment of hypertension." (PMID 24959250, 2014). "In view of the fact that hormonal changes during pregnancy can be related to central imbalances that can lead to hypertension, we measured ACE and ACE2 activity, components of the renin-angiotensin system (RAS) in the total tissue extracts from the hypothalami of the studied groups." (PMID 25405471, 2014). "Fourth, alterations within the renin-angiotensin-aldosterone system (RAAS) may contribute to the development of sarcopenia and hypertension." (PMID 24489804, 2014). "Another study suggests that treatment with Co-Q10 (50 mg twice a day for ten weeks) in patients with essential hypertension reduced hypertension without affecting the plasma renin activity, serum and urinary sodium and potassium, and urinary aldosterone." (PMID 24932457, 2014). "A recent work from Navar’s group and our collaborator Casarini’s group revealed that the maintenance of high blood pressure in 2K1C is dependent of an imbalance between high levels of ACE/Ang II and low levels of ACE2/Ang 1–7, both being influenced by renin activity." (PMID 25223948, 2014). "During a workup for hypertension and hypokalemia, serum aldosterone concentration of the patient was found to be 11 ng/dl with a plasma renin activity (PRA) of 0.25 ng/ml per h, with an aldosterone:renin ratio of 44 while taking lisinopril." (PMID 24616772, 2013). "Ang II, the fundamental determinant in the renin-angiotensin system is formed by the action of angiotensin converting enzyme (ACE) on angiotensin I, and is a crucial factor in the etiology of hypertension and resultant changes in cardiac morphology and remodeling." (PMID 24077237, 2013). "Circulatory and tissue renin-angiotensin systems (RAS) play a central role in cardiovascular (CV) and renal pathophysiology, making RAS inhibition a logical therapeutic approach in the prevention of CV and renal disease in patients with hypertension." (PMID 23866091, 2013). "This can be attributed to the treatment of hypertension, such that drugs that target the renin-angiotensin system may reduce blood pressure and inflammation in T2DM patients with hypertension." (PMID 23762057, 2013). "Mice lacking the VDR exhibit hypertension and cardiac hypertrophy due to increased renin expression and plasma angiotensin II production." (PMID 23349943, 2013). "The renin-angiotensin-aldosterone system (RAAS) plays pivotal roles in the pathogenesis of chronic kidney disease (CKD) progression and its increased complications such as hypertension (HT) and cardiovascular diseases (CVD)." (PMID 23577328, 2013).
Hypertension (continued). "Although the classical triad of JGCT is poorly controlled hypertension, elevated renin level, and renal mass, some cases had been reported which lacked hypertension and/or hypokalemia." (PMID 23607027, 2013). "Aliskiren, a novel successful non-peptide-like renin inhibitor, has been approved for hypertension treatment." (PMID 23825541, 2013). "As an inhibitor of renin, aliskiren inbitits the down-stream signals, including PRA, angiotensin I and angiotensin II, which may in turn exert some benefits in lowering hypertension." (PMID 23922924, 2013). "Currently, the levels of plasma renin activity (PRA), angiotensin II (Ang II), and aldosterone (ALD) have become the key indicators for diagnosis, treatment, and clinical research about both primary and secondary types of hypertension." (PMID 24349612, 2013). "Aldosterone is an endogenous mineralocorticoid receptor (MR) agonist synthesized in the adrenal glomerular layer as a final product of the renin-angiotensin-aldosterone system (RAAS); it is strongly involved in the development of hypertension due to excessive sodium retention." (PMID 23097668, 2012). "Human renin and AGT double transgenic mice exhibit Ang II-dependent hypertension, which can be attenuated by AVP antagonist suggesting an interaction between the brain RAS and AVP in hypertension." (PMID 23316344, 2012). "The development of hypertension in various animal models of hypertension, such as the spontaneously hypertensive rat (SHR), the renin transgenic (TGR mRen2) rat, the Dahl salt-sensitive rat, and the deoxycorticosterone acetate- (DOCA-) salt rat, is associated with increases in sympathetic activity." (PMID 22216059, 2012). "Moreover, the renin-angiotensin system in RVLM also plays an active role in central regulation of cardiovascular function and pathogenesis of hypertension." (PMID 22897791, 2012). "Animal studies suggest that local adipocyte-mediated activity of the renin-angiotensin-aldosterone system (RAAS) contributes to circulating levels, and may promote the development of obesity-related hypertension in rodents." (PMID 22475205, 2012). "Taking the first and last genes in the list as examples, for each term (i.e., MDM2 and ING1 for apoptosis, and REN and ACE2 for hypertension), we found strong evidence in the most recent supporting publications for linking these non-gold standard genes to the query." (PMID 23282288, 2012). "An advantage to using the C57BL/6 mouse for the induction of RAS-dependent hypertension is that it is a prototype of strains with a single renin gene, that is, this mouse does not behave differently from the rat in the 2K1C model of renovascular hypertension." (PMID 23193440, 2012). "We have also shown raised plasma renin activity in healthy subjects without hypertension after administration of PTH." (PMID 21403888, 2011). "Growth is affected with worsening renal function, hypokalaemia, hypochloraemic metabolic alkalosis, hypocalcemia, hypomagnesemia, increased levels of aldosterone, renin and angiotensin without hypertension and lack of responses to vasopressors." (PMID 20882176, 2010). "In March 2007, the US Food and Drud Administration approved a new renin-angiotensin blocker (aliskiren, a direct renin inhibitor) for the treatment of hypertension in humans without renal dysfunction." (PMID 19390623, 2009). "Renin plays a crucial role in the regulation of blood pressure, and the renin gene (REN) is considered as a good candidate quantitative trait locus involved in the etiology of essential hypertension." (PMID 19243623, 2009). "One significant target in this context is the renin–angiotensin–aldosterone system (RAAS), a crucial regulator of blood pressure and fluid homeostasis, and a central focus in the treatment of chronic cardiovascular conditions such as arterial hypertension (AH) and heart failure (HF)." (PMID 41009387, 2025).
Hypertension (continued). "The present study might provide future options for selecting SPARC inhibitors in patients with hypertension and hypertensive organ damage who are not eligible to receive renin–angiotensin system inhibitors because of side effects or contraindications." (PMID 40362650, 2025). "At present, it is thought that obesity-driven fat accumulation leads to hypertension primarily through chronic vascular inflammation, physical compression of the kidney, and overactivation of the sympathetic nervous system (SNS) and the renin–angiotensin–aldosterone system." (PMID 40944173, 2025). "The search strategy combined Medical Subject Headings (MeSH) and free-text terms: “renin inhibitors”, “direct renin blockade”, “aliskiren”, “angiotensin-converting enzyme inhibitors”, “ACE inhibitors”, “angiotensin receptor blockers”, “ARB”, and “hypertension”." (PMID 41409925, 2025). "Drugs used for the treatment of hypertension were not in the top three, probably because of the different clinical approaches that can be chosen (e.g., diuretics, agents acting on the renin–angiotensin system, beta-blocking agents, and cardiac insufficiency therapy)." (PMID 40363893, 2025). "Moreover, a dysregulation of the renin–angiotensin–aldosterone system (RAAS) has been documented in patients with MASLD, which plays a role in the development of hypertension, hypertension-mediated organ damage, increased vascular resistance, and cardiac remodeling." (PMID 40869400, 2025). "This may reflect confounding by indication, as heart failure as well as hypertension increase antidiuretic hormone (ADH) production and stimulate the renin–angiotensin–aldosterone system (RAAS), both of which promote water reabsorption, thus increasing hyponatremia risk." (PMID 40748456, 2025). "Hypertension therapy in older adults is often suboptimal, which can impact on cardiac complications after noncardiac surgery by failing to reduce activation of the renin–angiotensin system and inflammation." (PMID 39709293, 2025). "Hence, the most common presentation of 17OHD is an adolescent girl without secondary sexual characteristics or menses and low-renin hypertension." (PMID 39020240, 2024). "Of note, one patient needed no hypertension medication, while ten others tolerate a renin-angiotensin blocking drug (for most of them, an angiotensin receptor blocker), which is important both for hypertension control and for the long-term prognostic effect of these drugs." (PMID 38236490, 2024). "Inhibitors of the renin–angiotensin–aldosterone system (RAAS), such as ACE inhibitors (ACEi), angiotensin-II receptor blockers and mineralocorticoid receptor antagonists, reduce morbidity and mortality in hypertension, congestive heart failure and chronic kidney disease." (PMID 39708241, 2024). "In terms of blood pressure regulation mechanisms, the renin–angiotensin system (RAS) is the most important blood pressure regulation system in humans and other mammals; the regulation of key factors in the RAS has become a research direction of great interest in the treatment of hypertension." (PMID 39796531, 2024). "In one study done in a Japanese population with hypertension, although low renin was not a study inclusion criterion, authors report that the majority of participants had low renin (mean active plasma renin ranged from 5.7 mU/L to 10.1 mU/L in the different treatment groups)." (PMID 38200100, 2024). "According to a recent study, peptides derived from casein may have anti-hypertensive properties by inhibiting enzymes responsible for hypertension, especially renin and angiotensin II converting enzyme (ACE) involved in the renin-angiotensin-aldosterone (RAAS) pathway." (PMID 39064766, 2024).
Hypertension (continued). "The underlying mechanisms may involve endothelial damage, vascular dysfunction, renal impairment, hyperactivity of the sympathetic nervous system (SNS), and disturbances in the renin-angiotensin-aldosterone (RAAS) induced by oxidative stress, ultimately leading to the development of hypertension." (PMID 38544757, 2024). "The renin-angiotensin-aldosterone system (RAAS) is a circulatory system that is crucial for regulating fluid balance as well as sodium and potassium homeostasis, and its dysregulation may lead to arterial hypertension." (PMID 38410670, 2024). "Contrary to the majority of evidence supporting the importance of NOX1 and NOX2 in short-term Ang II-induced hypertension, a different model of life-long renin overexpression produces HTN regardless of NOX1 or NOX2, possibly because chronically elevated Ang II causes developmental changes." (PMID 39765782, 2024). "The role of the renin-angiotensin-aldosterone system (RAAS) as a mediator of cardiovascular pathology in PHPT is unclear, as is the question whether successful parathyroidectomy (PTX) mitigates hypertension (HT), and left-ventricular (LV) dysfunction." (PMID 37492200, 2023). "The 2020 KDIGO guidelines clearly recommend the long-term use of renin-angiotensin system inhibitors (RASI) for IgAN patients with urinary protein regardless of whether they have hypertension or not, and RASI drugs provide supportive care." (PMID 36998610, 2023). "After the adrenal gland is removed, although there is no aldosterone from the tumour, the persistence of adipocyte-related aldosterone secretion independent of renin may explain the unresolving hypertension." (PMID 37452142, 2023). "Consequently, in the present study, we further observed that long-term DOCS-treated one-renin gene mice developed chronic renal inflammation, fibrosis, and dysfunction without hypertension." (PMID 38069178, 2023). "In the same study, they monitored plasma renin and serum sodium levels, and concluded that in ARPKD, arterial hypertension is probably not driven by renin but by an increase in intravascular volume, as suggested by hyponatremia, which they observed frequently, especially in younger children." (PMID 37006611, 2023). "Nevertheless, the estimation of these parameters, e.g., the renin activity, is difficult to determine and is not routinely assessed by every biochemical laboratory and definitive diagnoses should be confirmed in specialized centers for hypertension." (PMID 36553213, 2022). "First, we did not consider the effects of changes in renin level or the incidence of chronic diseases, such as hepatitis and cancer, which could affect the incidence of hypertension during the follow-up period." (PMID 35448080, 2022). "We are dealing with hypertensive patients at diagnosis and sometimes it is difficult to establish the duration of hypertension, considering that not everyone has had their blood pressure measured and the aldosterone to renin ratio evaluated before they first noticed blood pressure was high." (PMID 34847293, 2022). "Since EP and IP receptors are the main regulators of blood pressure via prostaglandins through control of vascular tone, sodium excretion, and renin release, and not the DP1, we considered that the proposed extract combination is unlikely to influence blood pressure or to cause hypertension." (PMID 35209016, 2022). "In addition, the inhibitory effect of elevated blood pressure on renin synthesis and secretion is absent, resulting in increased plasma renin concentrations despite hypertension." (PMID 35511367, 2022). "The presence of hyperkalemic metabolic acidosis with inadequately low urinary potassium excretion, which was not explained by CKD alone, low-renin hypertension with aldosterone that was inadequately low in for hyperkalemia, and parental consanguinity led us to consider PHA II." (PMID 35093948, 2022).
Hypertension (continued). "In addition, the duration of hypertension was relatively longer in patients 1, 2, 5 and 7, which might have led to elevation of PRA via the activation of the renin-angiotensin system." (PMID 35482752, 2022). "Our data strongly suggest that the development of 2K1C Goldblatt hypertension is not solely dependent on increased renin expression and renin release from the clipped kidney into the circulation, where Ang II induces 2K1C hypertension by activating AT1a receptors in other target tissues." (PMID 36555438, 2022). "Thus, there were no patients with typically renin-mediated hypertension (e.g., unilateral renal artery stenosis) or low-renin hypertension (e.g., monogenic hypertension or primary aldosteronism)." (PMID 35627493, 2022). "The new model consisted of nine preoperative variables, including age, male gender, left ventricular ejection fraction, hypertension, hemoglobin, uric acid, hypomagnesemia, and oral renin-angiotensin system inhibitor and non-steroidal anti-inflammatory drug within 1 week before surgery." (PMID 34372744, 2021). "Given that minocycline treatment-induced programmed hypertension coincided with increased Oflr78 and renin expression, further research is needed to clarify whether the interplay between SCFA receptors and RAS could be a potential target for preventing hypertension of developmental origin." (PMID 33800916, 2021). "Thus, the objective of this study is aimed at investigating whether DOX prevents cardiovascular pathology and attenuates hypertension in DOCA-salt rats, a renin-independent model of hypertension." (PMID 34578849, 2021). "•Rule out renin-mediated hypertension in hypertension following abdominal packing." (PMID 33857767, 2021). "The SHR strain is considered the best model to mimic primary human hypertension considering a lot of shared features, such as similar dynamics of the disease and the activity of crucial systems, such as the sympathetic nervous system (SNS) and the renin–angiotensin–aldosterone system (RAAS)." (PMID 35111064, 2021). "In mice, while the absence of monocyte lineage prevents angiotensin II-driven hypertension, the overactivation of the renin-angiotensin system results in renal and vascular accumulation of proinflammatory macrophages resulting in increased oxidative stress and its associated tissue damage." (PMID 34950686, 2021). "However, non-renin mediated hypertension is expected to display suppressed renin-release, and, in addition, endogenous sympathetic over-activity should cause tachycardia, either of which were not consistent with the presentation in this case." (PMID 33857767, 2021). "Additionally, with prolonged exposure to high volume shunts, renal hypoperfusion may occur resulting in upregulation of the renin-angiotensin-aldosterone system (RAAS) and consequently systemic hypertension." (PMID 34640535, 2021). "One hypothesis postulates that ACE inhibitors and/or ARBs, taken by approximately 65% of our participants with hypertension, may mediate changes in baseline inflammation or in ACE2 receptor expression or affinity through the renin-angiotensin-aldosterone system." (PMID 34871308, 2021). "Our previous studies have proved that activated renin–angiotensin system (RAS) triggers the overproduction of ROS and increases the NAD(P)H oxidase activity and its subunits (NOX2 and NOX4) in the PVN, which produced the excessive ROS during the development of hypertension." (PMID 34899311, 2021). "The renin-angiotensin system (RAS) and hypertension also may be influenced by renal IR injury." (PMID 33986960, 2021). "There has been no systematic report on whether the targeted use of renin angiotensin inhibitors can effectively control the symptoms of refractory hypertension in patients with dissection related RAS." (PMID 33969023, 2021). "Nor did it decrease in DOCA-salt model mimicking low-renin human hypertension." (PMID 33651165, 2021).